TNF (tumor necrosis factor)
Diseases named in the same sentence as TNF in open-access papers (continued):
Sharing a sentence is not in itself a finding about the gene and the disease.
pulmonary embolism (11 papers, 2018 to 2025). The obstruction of the pulmonary artery or one of its branches by an embolus, sometimes associated with infarction of the lung. "High-dose tofacitinib, for example, was associated with a dose-dependent increase in pulmonary embolism risk (up to sixfold at 10 mg BID) compared to TNF blockers, even though differences in simple DVT were less pronounced." (PMID 41404585, 2025). "This warning was based on interim data from an ongoing safety study that showed a higher risk of pulmonary embolism and overall mortality in patients receiving the higher dose compared to those receiving a TNF inhibitor." (PMID 37755540, 2023). "There was one death during follow-up: an IBD1 patient who was due to start anti-TNFα therapy for chronically active disease died from a pulmonary embolism." (PMID 31030191, 2019). "Apelin, fibulins, haemopexin, a2-macroglobulin, Ig a1-chain C region, TNF-α, HMGB1, neutrophil-to-lymphocyte ratio and albumin are among the other biomarkers whose effectiveness has been investigated in the diagnosis of pulmonary embolism." (PMID 36115957, 2022). "Our experiments indicate that in the acute pulmonary embolism combined with shock model, the TLR4/NF-κB/HIF-1α signaling pathway is activated, which might stimulate the upregulation on the expression of downstream Gal-3, and the release of inflammatory factors such as IL-6 and TNF-α." (PMID 40666114, 2025).
reactive arthritis (11 papers, 2012 to 2025). Reactive arthritis (ReA) is an autoimmune disorder belonging to the group of seronegative spondyloarthropathies and is characterized by the classic triad of arthritis, urethritis and conjunctivitis. "We successfully treated a patient with reactive arthritis induced by active extra-articular tuberculosis with a TNF inhibitor after sufficient antitubercular treatment." (PMID 31804308, 2019). "In conclusion, we successfully treated our patient having reactive arthritis induced by active extra-articular tuberculosis with a TNF inhibitor after sufficient antitubercular treatment." (PMID 31804308, 2019). "Current opinion is that because TNF-α drives the pathogenesis of reactive arthritis and suggests TNF-α antagonists will be efficacious therapeutic tools." (PMID 22229035, 2012).
relapsing-remitting multiple sclerosis (11 papers, 2011 to 2024). The most common clinical variant of multiple sclerosis, characterized by recurrent acute exacerbations of neurologic dysfunction followed by partial or complete recovery. "A double-blind placebo-controlled phase II study of 168 patients with relapsing-remitting multiple sclerosis (MS) showed that anti-TNF-treated patients experienced a significant number of exacerbations in comparison to controls." (PMID 23573450, 2013). "TNF-α mRNA expression in blood mononuclear cells is correlated with disease activity in relapsing-remitting MS, while high IL-6 levels in the CNS and TNF-α release in astrocytes are correlated with the development of EAE in rats." (PMID 21410936, 2011). "However, Phase II clinical trials in which patients with relapsing-remitting MS were administered Lenercept, a sTNF-RI fusion protein that neutralizes TNF-α were halted when disease acutely worsened." (PMID 22933014, 2012). "The increase of pro-inflammatory cytokines interferon gamma (IFN-γ), tumor necrosis factor alpha (TNF-α) and interleukin 6 (IL-6) prior to and during clinical relapse have been widely demonstrated in the literature in relapsing-remitting MS (RRMS) compared to controls." (PMID 34589733, 2021).
Sleep disturbance (11 papers, 2010 to 2023). An abnormal pattern in the quality, quantity, or characteristics of sleep. "The inflammatory cytokines, IL-6 and TNFα, were the most strongly associated with deployment-related pathology like more severe PTSD, problem drinking, increased neurobehavioral symptoms, and sleep dysfunction, as well as maladaptive functional outcomes." (PMID 35217643, 2022).
temporal lobe epilepsy (11 papers, 2013 to 2025). A localization-related (focal) form of epilepsy characterized by recurrent seizures that arise from foci within the temporal lobe, most commonly from its mesial aspect. "Toll-like receptor 1 (TLR1) was also shown to be predictive of seizure frequency in our study and is implicated in temporal lobe epilepsy as a key transduction receptor of neuro- inflammation-induced epileptogenesis through glial production of inflammatory cytokines, IL-1β and TNF-α." (PMID 38166692, 2024). "Crocin can increase the BDNF level in the cortex of temporal lobe epilepsy and reduce the content of tumor necrosis factor α (TNF-α) in the hippocampus, thereby playing an antiepileptic role." (PMID 38633914, 2024). "Among worldwide research, higher expression of TNF-α in CD4+ lymphocytes is reported in patients with temporal lobe epilepsy than controls." (PMID 32403392, 2020). "While, suppression of IL-1β or TNF-α expression could lead to prevention or delay of seizures, and exerts neuroprotection in a rat model of temporal lobe epilepsy." (PMID 29311813, 2017). "Moreover, inhibition of IL-1β or TNF-α expression may lead to prevention or delay of seizures and play a neuroprotective effect on a rat model of temporal lobe epilepsy." (PMID 32982679, 2020). "Pro-inflammatory cytokines — including interleukin-1β (IL-1β), interleukin-6 (IL-6), and tumor necrosis factor-α (TNF-α) — are significantly elevated in the serum and cerebrospinal fluid of patients with temporal lobe epilepsy and related syndromes." (PMID 40821023, 2025).
ventricular dilatation (11 papers, 2015 to 2024). "TNFα has been shown to induce cardiomyocyte dysfunction, cardiomyocyte fibrosis, and negative inotropic effects, and its elevation is associated with cardiac fibrosis, ventricular dilatation, and mortality." (PMID 36859608, 2023). "Furthermore, at physiological concentrations, intracerebroventricular delivery of metHgb activates TLR4 homodimers or TLR4/2 heterodimers, promoting nuclear translocation of NF‐κB as well as secretion of TNFα and IL‐1β, and is sufficient to cause ventriculomegaly." (PMID 39450988, 2024). "It has been reported that increased TNF-α levels were related to ventricular dilatation, cardiac fibrosis, and mortality." (PMID 35669500, 2022). "This explains why treatment with anti TNF is effective to reverse the process of ventricular dilatation only when administered in the early stage, and the apparent contradiction of the worsening of the clinical condition induced by biological therapy with anti-TNF in patients with advanced CHF39." (PMID 29651025, 2018). "Newborns with hyperEPO only were not at significantly different risk of ventriculomegaly, whereas those with ISSI only (MPO, IL-1 β, IL-6, TNF- α, IL-8, MCP-1, VEGF, VEGF-R1, orange) were 2–5 times more likely to have ventriculomegaly than children without either hyperEPO or ISSI." (PMID 25793991, 2015).
antiphospholipid syndrome (10 papers, 2009 to 2025). A disorder caused by the presence of autoantibodies directed against phospholipids, causing a hypercoaguable state, which may result in blood clots, stroke, heart attack, and in women, significant pregnancy-related complications, including miscarriage and still birth. "We deliberated a case report of seven cases to investigate whether inhibitors of tumor necrosis factor-α (TNF-) could reduce pregnancy dangers caused by antiphospholipid syndrome (APS)." (PMID 40979093, 2025). "Immunological factors including peripheral and uterine natural killer cells, Th1/Th2 ratio, tumor necrosis factor alpha (TNF-α) levels, auto-antibodies, antiphospholipid syndrome, hereditary thrombophilia as well as infection are considered to participated in the pathogenesis of RIF." (PMID 36911409, 2023). "The administration of TNF-α increases abortion rates, and blockage of TNF-α has been identified as a potential therapy for the pregnancy complications of antiphospholipid syndrome in murine abortion models." (PMID 19564935, 2009). "Sera from 30 patients with antiphospholipid syndrome (11 primary and 19 secondary APS), 35 subjects with pregnancy morbidity, and 30 healthy women were analysed for HMGB1 and its putative receptor RAGE (sRAGE) by Western blot and for TNF-α by ELISA." (PMID 29410969, 2017).
aphthous ulcers (10 papers, 2012 to 2024). "The aim was to evaluate the salivary levels of TNF-α in patients with recurrent aphthous stomatitis." (PMID 29732020, 2018). "In this study, Corchorus olitorius seed extract displayed remarkable wound healing activity in the treatment of recurrent minor aphthous ulceration (RMAU) by accelerating wound closure rate, enhancing TGF-β, as well as TNF-α, expression, and suppressing inflammatory markers (TNF-α, and IL-1β)." (PMID 36296628, 2022).
autoinflammatory syndrome (10 papers, 2016 to 2025). A group of disorders of the innate immune system characterized by attacks of seemingly unprovoked inflammation without significant levels of either autoantibodies or autoreactive T cells more characteristic of autoimmune disease. "Specifically, TNF-α induces the production of IL-1β and IL-6, with the former being a crucial mediator of the inflammatory response, causing various autoinflammatory syndromes, and the latter being secreted by T cells and macrophages to stimulate the immune response." (PMID 27382402, 2016). "Significantly, the fact that the here-described OTULIN-related autoinflammatory syndrome/ORAS can be treated with TNF-neutralizing antibodies suggests a potential therapeutic strategy to treat conditions caused by excessive M1-linked polyUb signaling." (PMID 27523608, 2016). "Limiting TNF-based pro-inflammatory responses also improves symptoms in patients homozygous for rare variants in OTULIN and suffering from an autoinflammatory syndrome called OTULIN-related autoinflammatory syndrome or otulipenia." (PMID 37589075, 2023). "However, the development of CD and subsequent treatment with TNF-α inhibitors may have augmented the effects of the NLRP12 variant on inflammasomes, leading to clinical features resembling autoinflammatory syndromes." (PMID 35538558, 2022). "Given the similarity of her neuropsychiatric and joint symptoms to autoinflammatory syndrome and her lack of responses to TNF-α inhibitors, infliximab was discontinued." (PMID 35538558, 2022). "However, unlike the monogenic autoinflammatory syndromes where a clear multiple change in the inflammasome structure/function is demonstrated, NDs display several proinflammatory abnormalities, mainly driven by IL-1, IL-17, and tumor necrosis factor-alpha (TNF-a)." (PMID 31281845, 2019).
bladder tumors (10 papers, 2003 to 2023). "The expression levels of TLR4, TGF-β1, IFN-γ, and TNF-α were evaluated in samples of urinary bladder tumors and unaffected adjacent tissue from 50 patients." (PMID 40778061, 2023). "It is important to note that increased TNF-α expression has been reported in recurrent, larger bladder tumors as well as in tumors that show progression in grade and stage." (PMID 23374147, 2013). "If the presence of TNF+488A or TNF−859T affects the development of bladder tumours to make them generally less well differentiated, then we would expect to see more G3 as well as G2 tumours." (PMID 12966432, 2003). "TNFα has also been demonstrated in bladder tumour biopsies by immunohistochemistry and has been shown to be involved in both the local and systemic immune response to the intravesical instillation of bacille Calmette-Guerin (BCG)." (PMID 12966432, 2003). "As TNF alpha is tumor-promoting, the estrogen-mediated repression of TNF alpha may support a stronger anti-tumor immune microenvironment in bladder tumors of patients with female gonads." (PMID 37666817, 2023). "Recombinant TNF has been effectively used to treat bladder tumors in vivo." (PMID 22536907, 2012). "Our genetic results demonstrate that CG does not have the classic chromosomal variation observed in bladder tumors, reveal the specific effects of TNF in KRT15 epithelial cells, and identify a new population of PIGR epithelial cells with high immunogenicity." (PMID 36814917, 2023). "Furthermore, in vitro assays revealed that either BCG, Zoledronate, or anti-BTN3 agonistic antibody treatment of bladder tumor cells induced Vδ2 T-cell cytolytic (CD107a+) and cytokine-production (IFN-γ and TNF-α)." (PMID 36002184, 2022). "Notably, cytotoxic CD4+ T cells in bladder tumors were also polyfunctional, with over half of cells able to express both IFN-γ and tumor necrosis factor (TNF)-α with ex vivo stimulation." (PMID 34910940, 2021).
Chagas cardiomyopathy (10 papers, 2010 to 2025). A disease of the cardiac muscle developed subsequent to the initial protozoan infection by trypanosoma cruzi. "Research suggests that individuals at high risk of sudden death in Chagas cardiomyopathy exhibit elevated serum levels of IFN-γ, TNF-α, IL-6, IL-2, IL-10, and IL-4 compared to those at low risk." (PMID 39907396, 2025). "The presence of TNF has been observed in histopathological studies in the hearts of patients who died from Chagas cardiomyopathy." (PMID 38543309, 2024). "Interestingly, TNF and endothelin-1 are well-established biomarkers of pathogenesis in experimental T. cruzi infection and indicators of severity in Chagas cardiomyopathy." (PMID 40936920, 2025). "The individuals with an indeterminate state had higher IL-10 expression, whereas the Chagas cardiomyopathy group presented the highest inflammatory cytokine expression (IFN-γ, TNF-α, IL-6 and IL-1β)." (PMID 38133693, 2023). "Our study also aimed to assess the plasmatic levels of TNFα, IL6 andendothelin 1, in patients with different clinical forms of Chagas cardiomyopathy.These biomarkers have been described to be elevated in Chagas cardiomyopathy." (PMID 20877635, 2010). "Furthermore, the implication of TNF and transforming growth factor beta (TGF-β) in Chagas cardiomyopathy has been pointed out." (PMID 38543309, 2024). "The lack of this microRNA seems to decrease IFN-γ and TNF-α in the acute stage of Chagas cardiomyopathy in mice heart tissue." (PMID 36072583, 2022).
chordoma (10 papers, 2016 to 2026). Chordomas are rare malignant tumors arising from embryonic remnants of the notochord in axial skeleton. "A notable target is the TNF signaling pathway, which was shown to activate metastatic and tumor-promoting inflammatory pathways in chordoma." (PMID 36033338, 2022). "This study tends to identify differentially expressed genes (DEGs) before and after treatment of TNF-α in chordoma cell line, providing a new target for future molecular therapy of chordoma." (PMID 32011476, 2020). "Exposure of chordomas to TNF-α upregulates not only its own gene expression but also LIF expression, and vice versa; both cytokines are correlated with increased tumor size, implicating these factors in chordoma growth." (PMID 32733369, 2020). "Considering the treatment of TNF-α as an inducing factor, the differential genes before and after TNF-α treatment can be equated with the key genes for the development of chordoma." (PMID 32011476, 2020). "Interesting, several cytokines including interleukin-6 and tumor necrosis factor-alpha were reported to be elevated in chordoma patients, suggesting the potential role of cytokines in chordoma progression." (PMID 33046024, 2020). "Expression of either TNF-α or LIF in chordoma cell lines promoted cell migration, invasive capabilities, and anchorage-independent growth, demonstrating their pro-tumoral and metastatic potential." (PMID 32733369, 2020). "This cytotoxic effect of eosinophils on chordoma cells could be inhibited by blocking TNF-α via neutralizing antibodies (Certolizumab pegol, MCE, HY-P9953), which resulted in a 22% decrease in apoptosis rate at 5 μg/ml and 41% decrease at 10 μg/ml." (PMID 41387915, 2025). "In summary, this study demonstrated that eosinophils in chordoma may exert an inhibitory effect on tumor proliferation by secreting the inflammatory cytokine TNF-α, which promotes tumor cell apoptosis." (PMID 41387915, 2025). "TNF-α may serve as a prognostic marker for chordoma progression because TNF-α increased the migration and invasion of chordoma cells." (PMID 34016788, 2021). "TNF-α-exposed chordoma cells displayed increased programmed death-ligand 1 (PD-L1) but downregulated T expression; brachyury-targeted treatments may be impacted as a result." (PMID 32733369, 2020). "Pro-angiogenic and anti-apoptotic pathways were also upregulated with longer TNF-α exposure, which may contribute to the survival and metastatic potential of chordomas." (PMID 32733369, 2020). "Recent studies have shown that the proliferation and invasion ability of chordoma after Tumor necrosis factor alpha (TNF-α) treatment is enhanced, which may activate the gene pathway involved in the development of chordoma." (PMID 32011476, 2020). "Further research showed that eosinophils could inhibit chordoma cell proliferation by inducing apoptosis and secreting inflammatory cytokines, and the apoptotic effects could be reversed by blocking with anti-TNFα Ab, further confirming the antitumor role of eosinophils." (PMID 41387915, 2025). "For example, suppressed miR-665 expression may contribute to the activation of TNF signaling pathways, which may help the immune evasion of the chordoma cells through stabilizing the undifferentiated phenotype, and/or through immunoediting in the tumor microenvironment." (PMID 36033338, 2022). "Differential gene expression analysis post-TNF-α exposure demonstrated upregulation of the phosphoinositide 3-kinase (PI3K)/Akt, Ras, and Ras-related protein 1 (Rap1) signaling pathways, implicated in progression of chordomas and other malignancies, respectively." (PMID 32733369, 2020). "Our findings align with previous research on miRNA–cytokine networks in spinal disorders, including miR-17 regulation of TNF-α and IL-6 in LDDD and TNF-α–mediated progression in chordomas." (PMID 41535614, 2026).
chordoma (continued). "Previous studies suggested that some cytokines and chemokines, including TNFα, LIF, IL-6 and IL-8 played important roles in the immune microenvironment of chordoma, but relatively few studies had been conducted." (PMID 38983929, 2024). "stained some kinds of cytokines in 14 chordoma tissues and found that the expression level of TNFα in chordoma was negatively correlated with the survival time of patients, and positively correlated with higher LIF and PD-L1expression in chordoma." (PMID 38983929, 2024). "Epithelial marker expression was downregulated while mesenchymal marker expression was upregulated following exposure to TNF-α, implicating TNF-α in the chordoma epithelial-mesenchymal transition." (PMID 32733369, 2020). "Recently, it had been discovered that kinds of cytokines and chemokines, such as TGFβ, TNFα, CCL5, IL-8, IL-6 and LIF, also as important mediators of cellular interactions, had been found to be highly expressed in chordomas and play important roles in the immune microenvironment." (PMID 38983929, 2024). "This pathway is CD134 also known as TNF alpha super family which could be targeted using agonistic anti-OX40 antibodies to promote T cell activation and kill chordoma cells." (PMID 34885223, 2021). "Finally, resistance to cytotoxic chemotherapies also increases in these chordoma cells exposed to LIR and TNF-α." (PMID 32733369, 2020).